RUNX2 (RUNX family transcription factor 2)
Diseases named in the same sentence as RUNX2 in open-access papers (continued):
Sharing a sentence is not in itself a finding about the gene and the disease.
apical periodontitis (2 papers, 2025). "Lithium accelerated healing of apical periodontitis in an animal model 40,44 showed that LiCl caused an increase in osteogenic markers, such as Runx2 and Osterix." (PMID 41294202, 2025). "This study assessed bone regeneration in diabetic rats with apical periodontitis through histopathological analysis of osteoblasts and immunohistochemical analysis of runt-related transcription factor 2 (Runx2) and Osterix." (PMID 39687469, 2025). "Umbilical cord mesenchymal stem cells improve bone regeneration in diabetic animal model with apical periodontitis, in terms of osteoblasts, Runx2 and Osterix." (PMID 39687469, 2025). "This study accepts our hypothesis that UCMSCs application in diabetic rats with apical periodontitis will increase the number of osteoblasts, Runx2 and Osterix expressions after 30 and 60 days." (PMID 39687469, 2025). "In this study, we studied whether UCMSCs induction in diabetic rats with apical periodontitis will positively affect bone regeneration by evaluating the changes in the number of osteoblasts and the expressions of Runx2 and Osterix after 30 and 60 days." (PMID 39687469, 2025). "Our proposed hypothesis is UCMSCs application in diabetic rats with apical periodontitis will increase the number of osteoblasts, Runx2 and Osterix expressions after 30 and 60 days." (PMID 39687469, 2025).
bladder urothelial cancer (2 papers, 2022 to 2023). "The association of RUNX2 with cancer-associated fibroblast infiltration as well as epithelial–mesenchymal transition was reported in a bladder urothelial cancer study." (PMID 37108164, 2023). "RUNX2 was overexpressed in tissue samples of bladder urothelial cancer, and immunohistochemistry further demonstrated the positive correlation of high RUNX2 levels with cancer-associated fibroblast biomarkers." (PMID 37108164, 2023). "In a tissue microarray study of 87 primary urothelial carcinoma and 17 control cases, we found that RUNX2 independently predicted early tumour recurrence in patients with bladder urothelial carcinoma." (PMID 36685927, 2022).
brachydactyly (2 papers, 2019 to 2022). A disease characterized by the presence of brachydactyly, including syndromic and non-syndromic forms. "We found that Runx2, a gene associated with brachydactyly, was differentially expressed between WT and MT group." (PMID 30651074, 2019).
chondroblastoma (2 papers, 2018 to 2023). A benign, chondroid-producing, well-circumscribed, lytic neoplasm usually arising from the epiphysis of long bones. "Most notably, the GCs of tenosynovial giant cell tumour are RUNX2-positive, while the GCs of chondroblastoma are RUNX2-negative throughout." (PMID 37509363, 2023). "RUNX2-expression has been shown in the neoplastic, mononuclear compartment of chondroblastoma, but not in the GCs, confirming our data." (PMID 37509363, 2023).
Cirrhosis (2 papers, 2023 to 2024). A chronic disorder of the liver in which liver tissue becomes scarred and is partially replaced by regenerative nodules and fibrotic tissue resulting in loss of liver function. "Then, human liver tissues were collected from individuals with non‐fibrosis or cirrhosis, and data consistently revealed that protein and mRNA levels of Runx2 were significantly upregulated in cirrhotic liver tissues." (PMID 37403784, 2023).
colorectal tumors (2 papers, 2019 to 2020). "This miRNA is frequently downregulated in colorectal tumors and acts predominantly as a tumor suppressor element by targeting phosphoinositide-3-kinase regulatory subunit 1 (PIK3R1) and Runt-related transcription factor 2 (RUNX2), both crucial for the development of tumors." (PMID 32083000, 2020).
cutaneous melanoma (2 papers, 2016 to 2018). A primary melanoma arising from atypical melanocytes in the skin. "First, analysis of 278 cutaneous melanomas (TCGA provisional RNASeqV2 RSEM) using the CBio Portal for cancer genomics indicated that AXL was co-expressed with RUNX2 (Pearson's correlation = 0.56)." (PMID 27102439, 2016).
disc degeneration (2 papers, 2021 to 2024). "We extended our investigation to determine if the lumbar disc degeneration observed was a direct consequence of Runx2, as well as the involvement of MMPs and ADAMTSs." (PMID 38877576, 2024). "In some experiments on mice that have led to disc degeneration, abnormal expression of type X collagen, increased apoptosis, inappropriate intervertebral disc ossification, and elevated expression of COL10A1, Runx2, MMP-13, etc. were observed in degenerative NP." (PMID 34307661, 2021).
dyslipidemia (2 papers, 2016 to 2017). "Pin1 associates with and controls key molecules (IRS-1, CRTC2, AMPK, eNOS, Runx2 and others) involved in metabolic functions or the development of metabolic syndromes." (PMID 27618008, 2016). "Therefore, it is concluded that high dose of fenofibrate may inhibit the expression of Runx2 gene in osteoblasts, and thus have a negative effect on the bones of T2DM mice with dyslipidemia." (PMID 29029615, 2017).
dysplasia (2 papers, 2016 to 2023). A usually neoplastic transformation of the cell, associated with altered architectural tissue patterns. "In humans, mutation of RUNX2 causes cleiocranial dysplasia and teeth abnormalities." (PMID 27645561, 2016).
endometriosis (2 papers, 2020 to 2024). The growth of functional endometrial tissue in anatomic sites outside the uterine body. "Our findings indicate that adenomyosis-related infertility is also a product of the significant upregulation of certain DEGs, such as RUNX2, increased in the endometrium of infertile women with endometriosis." (PMID 38195505, 2024). "At the same time, we calculated the diagnostic value of two hub DETFs (RUNX2 and BATF) for endometriosis." (PMID 33490107, 2020). "The results showed that RUNX2 and BATF were characterized by high specificity and sensitivity in the diagnostic of endometriosis." (PMID 33490107, 2020). "RUNX2 and BATF also had high diagnostic value in endometriosis." (PMID 33490107, 2020). "The Receiver Operating Characteristic (ROC) analysis was used to evaluate the sensitivity and specificity of RUNX2 and BATF for the diagnosis of endometriosis." (PMID 33490107, 2020). "By the PPI analysis, we found two hub TFs (RUNX2 and BATF) and they had significant differences in the analysis of different phases of the endometrium and the analysis of infertile and fertile females with endometriosis." (PMID 33490107, 2020). "Therefore, we had reasons to speculate that RUNX2 and BATF also played a role in the mechanism of endometriosis." (PMID 33490107, 2020).
eosinophilia (2 papers, 2022 to 2023). "Intriguingly, airway overexpression of mmu-miR-30a-3p suppressed Runx2 and Hmgb1 expression, and alleviated airway eosinophilia in a mouse model of allergic airway inflammation." (PMID 35093061, 2022). "Interestingly, an airway increases in mmu-miRNA-30a-3p inhibited HMGB1 and RUNX2 expression and reduced airway eosinophilia in an experimental animal model." (PMID 36675299, 2023). "We next analyze the correlation between epithelial RUNX2 expression and airway eosinophilia." (PMID 35093061, 2022). "This suggests that miR‐30a-3p may play a role in airway eosinophilia by targeting RUNX2." (PMID 35093061, 2022).
Familial adenomatous polyposis (2 papers, 2018 to 2023). Familial adenomatous polyposis (FAP) is characterized by the development of hundreds to thousands of adenomas in the rectum and colon during the second decade of life. "Supernumerary teeth have also been reported to be associated with various malformation syndromes, including APC-associated familial adenomatous polyposis (FAP), RUNX2-associated cleidocranial dysplasia, and TRPS1-associated tricho-rhino-phalangeal syndrome." (PMID 36901686, 2023).
fluorosis (2 papers, 2015 to 2017). "Aberrant change of Runx2 mediated signaling cascade is one of the decisive steps during the pathogenesis of fluorosis." (PMID 28125630, 2017). "Aberrant change in the Runt-related transcription factor 2 (RUNX2) mediated signaling cascade is one of the decisive steps during the pathogenesis of fluorosis." (PMID 26339601, 2015).
head and neck squamous cell carcinoma (2 papers, 2018 to 2022). A squamous cell carcinoma that arises from any of the following anatomic sites: lip and oral cavity, nasal cavity, paranasal sinuses, pharynx, larynx, and salivary glands. "The Runx2-mediated activation of PTHLH expression promotes the growth of head and neck squamous cell carcinoma." (PMID 35406121, 2022).
intervertebral disc degeneration (2 papers, 2012 to 2024). "We previously reported that mechanical loading specifically induces Runx2 within the Runx family and that Runx haploinsufficiency ameliorates the intervertebral disc degeneration that is caused by mechanical loading." (PMID 22927960, 2012).
ischemic stroke (2 papers, 2018 to 2022). A stroke disorder caused by obstruction of blood flow to the brain, due to thrombotic (local blood clot formation) or embolic (due to a blood clot or other material traveling from another site) event. "The interacting partners of HDAC4, MEF2, Runx2, SRF, HP1, ATF4, and NF-κB might also mediate its role in inhibiting neuronal death and promoting angiogenesis and neurogenesis in ischemic stroke." (PMID 30208931, 2018).
kidney failure (2 papers, 2019 to 2021). An acute or chronic condition that is characterized by the inability of the kidneys to adequately filter the blood. "Increments in RUNX2 expression tended to reflect the degree of kidney failure, though the differences between CKD groups were not significant." (PMID 31519772, 2019).
Lewis lung carcinoma (2 papers, 2017 to 2021). "Conditioned medium from LLC (Lewis lung carcinoma) cells can increase Runx2/VEGF/Dusp5 expressions in mast cells, and promote tumor angiogenesis." (PMID 34135893, 2021). "Conditioned medium from LLC (Lewis lung carcinoma) cells increase the expression of cell surface receptors and a pro-angiogenic Runx2/VEGF/Dusp5 axis in mast cells, which promotes tumor angiogenesis." (PMID 28968979, 2017).
metastasis (2 papers, 2018 to 2022). The spread or migration of cancer cells from one part of the body (where they first appeared) to another. "Interestingly, the four patients who received chemotherapy at some point before metastasis surgery had significantly lower RUNX2 immunoreactivity than patients who had never been treated with chemotherapy (p = 0.015), while TRAP immunoreactivity was unaffected." (PMID 29670000, 2018).
myelodysplastic syndrome (2 papers, 2022 to 2024). A clonal hematopoietic disorder characterized by dysplasia and ineffective hematopoiesis in one or more of the hematopoietic cell lines. "Recently, we identified polyploid giant cells expressing CD61, Syncytin-1, telomerase, Runx2, and macrophage markers (CD11b, CD68, and CD163) in the circulation of patients with myelodysplastic syndromes (MDS)." (PMID 38611120, 2024).
myeloid malignancies (2 papers, 2023). "The involvement of RUNX2 in PI3K/Akt signaling is well-known in myeloid malignancies, and the authors demonstrated that miR-338-3p significantly suppressed both RUNX2 mRNA and protein." (PMID 37304067, 2023).
myocardial infarction (2 papers, 2022). Gross necrosis of the myocardium, as a result of interruption of the blood supply to the area, as in coronary thrombosis. "We induced myocardial infarction in Wistar rats by permanent ligation of the left coronary artery and showed a change in the expression pattern of Notch-associated genes and Bmp2/Runx2 in post-MI tissues using RNA sequencing and RT-PCR." (PMID 35740305, 2022). "Here, we investigated the roles of Runx2 in cardiac remodeling after myocardial infarction (MI)." (PMID 36198906, 2022).
ossifying fibroma (2 papers, 2022 to 2023). A bone benign neoplasm that is located_in the mouth and results_in an overgrowth of gingival tissue due to irritation or trauma. "Further study showed that aged Men1f/f;Runx2‐Cre mice displayed lesion of ossifying fibroma (OF) in mandibular bone, with elevated levels of early osteoblast differentiation markers such as ALPL, COL1A1, RUNX2, and OSX." (PMID 35481717, 2022). "There are no data regarding RUNX2-expression for GC of non-ossifying fibroma, tenosynovial GC tumour or xanthogranuloma." (PMID 37509363, 2023).
pancreatic adenocarcinoma (2 papers, 2021 to 2023). "In pancreatic adenocarcinoma, knockdown of RUNX2 expression by specific shRNA caused a decrease in ASPC-1 cell migration, accompanied by phosphorylation activation of the MAPK and PI3K/AKT axes." (PMID 37108164, 2023). "In pancreatic adenocarcinoma, PI3K/AKT and MAPK signaling might be modulated by RUNX2 to augment cell growth." (PMID 37108164, 2023). "The mRNA expression levels of RUNX2, LAMC2 and FBXO32 showed significant differences between cancer and adjacent non-cancerous tissues especially in pancreatic adenocarcinoma (PAAD)." (PMID 34606473, 2021).
Peri-Implantitis (2 papers, 2019 to 2023). An inflammatory process with loss of supporting bone in the tissues surrounding functioning DENTAL IMPLANTS. "In peri-implantitis diagnostics and RUNX2 downregulation, functional overload plays an important role in the treatment of peri-implant disease." (PMID 37232785, 2023). "The RUNX2 gene in peri-implantitis is downregulated compared to healthy controls." (PMID 37232785, 2023).
psoriasis (2 papers, 2021). An autoimmune condition characterized by red, well-delineated plaques with silvery scales that are usually on the extensor surfaces and scalp. "In spite that these results must be validated in vitro and in vivo with a functional genomics approach, we propose FOXP2, RUNX2, NR2F1, ELF1 and HESX1 transcription factors (those with the highest FIF on each gene) as novel drug targets for psoriasis." (PMID 33898962, 2021).
pulpitis (2 papers, 2020). Inflammation of the dental pulp. "Furthermore, rDFSC-CM inhibited inflammatory cell infiltration in rat pulpitis and triggered Runx2 expression in some of the odontoblast-like cells surrounding the injured site, and these effects were conducive to the repair of inflamed dental pulp." (PMID 32746910, 2020).
rectal cancer (2 papers, 2017 to 2021). A primary or metastatic malignant neoplasm that affects the rectum. "RUNX2 also has been found to be associated with colon and rectal cancer." (PMID 28061442, 2017). "Additionally, BMPR2 rs2228545 and RUNX2 rs2819854 genotypes were associated with differential miRNA expression between rectal carcinoma and normal rectal mucosa." (PMID 28061442, 2017). "For example, PVT1, which is highly up‐regulated in rectal cancer cells and tissues, functions as a ceRNA in rectal cancer via the PVT1/miR‐30d‐5p/RUNX2 axis to promote cell proliferation and invasion." (PMID 34613665, 2021). "We previously found RUNX2, particularly interactions between these SNPs in RUNX2 and SMAD3, showed strong interaction to increase risk for rectal cancer, as well as prognostic implications." (PMID 28061442, 2017).
renal failure (2 papers, 2015 to 2021). "Arterial medial calcification is also induced in renal insufficiency by high serum levels of phosphate and calcium, which promote the Runx2/Cbfa-1 pathways." (PMID 26185749, 2015).
renal fibrosis (2 papers, 2018 to 2024). A final common manifestation of a wide variety of chronic kidney diseases characterized by glomerulosclerosis and tubulointerstitial fibrosis. "One study used full RUNX2 KO mice and demonstrated that RUNX2 prevents renal fibrosis by inhibiting EMT and that RUNX2 expression is decreased in UUO kidneys." (PMID 29759484, 2018). "Two independent groups previously reported the contradictory findings of Runx2 in renal fibrosis." (PMID 29759484, 2018). "Deletion of Runx1 in RTECs did not substantially affect the mRNA level of Runx2 mRNA in the UUO-induced renal fibrosis model." (PMID 29759484, 2018). "In the current study, we have demonstrated that expression of RUNX1, but not RUNX2 or RUNX3, was induced in the process of TGF-β-induced EMT in a SMAD3-dependent manner and in UUO-induced renal fibrosis in vivo." (PMID 29759484, 2018).
Saethre-Chotzen syndrome (2 papers, 2009 to 2025). Saethre-Chotzen syndrome (SCS) is an inherited craniosynostosis syndrome characterized by unilateral or bilateral coronal synostosis, facial asymmetry, ptosis, strabismus and small ears with prominent crus, among other less common manifestations. "Along the same lines, loss-of-function mutations in TWIST1, which directly antagonizes RUNX2 in the developing coronal suture, cause Saethre-Chotzen syndrome, characterized by coronal craniosynostosis." (PMID 40087503, 2025). "The majority of patients with Saethre-Chotzen syndrome (SCS) present loss-of-function mutations in transcription factor TWIST1 which is thought to negatively regulate FGFR1, 2 and 3 and the osteogenic transcription factor Runx2." (PMID 20108486, 2009).
sarcopenia (2 papers, 2024 to 2025). Progressive decline in muscle mass due to aging which results in decreased functional capacity of muscles. "A study found that the level of Runx2, a transcription factor essential to osteocyte maturation in patients with sarcopenia, was decreased, which was associated with a decrease in bone mineral density." (PMID 39186727, 2024).
spinal muscular atrophy (2 papers, 2020 to 2022). A motor neuron disease that affect the muscles, and characterized by muscle weakness and atrophy resulting from progressive degeneration and irreversible loss of the anterior horn cells in the spinal cord (i.e., lower motor neurons) and the brain stem nuclei. "HDAC inhibitors have also been applied to the treatment of genetic diseases such as increased acetylation of Runx2 in a calvaria defect model of the Runx2 null mouse and improving mRNA splicing to treat spinal muscular atrophy." (PMID 32796747, 2020).
ZIKV infection (2 papers, 2018 to 2020). "As been reported previously with a flavivirus, ZIKV infection induced a similar reduction in the gene expression of RUNX2 in infected cells." (PMID 32493723, 2020).
Zinc deficiency (2 papers, 2010 to 2024). A deficiency of the essential metal Zinc; an essential cofactor for many enzymes. "Dlx5 has been shown to induce expression of Runx2 in chicken, and Runx2, which is important for osteogenic differentiation, was recently found to be downregulated during zinc deficiency, and abnormally accumulated in osteoblasts from Slc39a13 null mice." (PMID 20937081, 2010).
Achilles tendinitis (1 paper, 2020). "In the present study, we observed that nesfatin-1 increased osteogenic gene (COL1A1, RUNX2, and ALP) expression in TDSCs in vitro and promoted heterotopic bone formation in Achilles tendinitis in vivo." (PMID 33344440, 2020).
adenovirus infection (1 paper, 2020). "Antxr1 expression was upregulated 3.7 times by Runx2-expressing adenovirus infection in the microarray analysis." (PMID 32244499, 2020).
adolescent idiopathic scoliosis (1 paper, 2025). A scoliosis with no known cause arising in adolescent. "Reduced mRNA and protein expression of RUNX2 were found in patients with adolescent idiopathic scoliosis (AIS) and decreased BMD." (PMID 40447997, 2025).
age (1 paper, 2025). A temporal measurement of the time period elapsed since an identifiable point in the life cycle of an organism. "Interestingly, the replicative senescence of VSMCs mediates their phenotypic transformation through runt-related transcription factor-2 (RUNX-2) and induces age-related medial arterial calcification." (PMID 41268564, 2025).
alcoholic liver diseases (1 paper, 2023). A disorder caused by damage to the liver parenchyma due to alcohol consumption. "The production of Runx2 was considerably higher in patients with liver cirrhosis caused by different aetiology, such as alcoholic liver disease, viral hepatitis and NAFLD." (PMID 37403784, 2023).